ECT2 (epithelial cell transforming 2)
Diseases named in the same sentence as ECT2 in open-access papers (continued):
Sharing a sentence is not in itself a finding about the gene and the disease.
squamous cell carcinoma (2 papers, 2021 to 2025). A carcinoma arising from squamous epithelial cells. "Previous reports have shown that ECT2 has Rho GTPase activity, which may promote the occurrence and progression of squamous cell carcinoma by mediating the overexpression of Rho A." (PMID 40655948, 2025).
Autoimmunity (1 paper, 2012). The occurrence of an immune reaction against the organism's own cells or tissues. "Both patients were unresponsive to steroids because the disease developed from ECT2 deletion, not through autoimmunity." (PMID 22552385, 2012).
B-cell lymphomas (1 paper, 2015). "Average FilGAP scores were significantly higher in B-cell lymphomas than those in PTCL, while FLNa, integrin β2, and ECT2 scores were significantly higher in PTCL than those in FL." (PMID 25641953, 2015).
cervical (1 paper, 2017). "The high expression of ECT2 in the region 3q may be implicated in cervical oncogenesis." (PMID 29312619, 2017).
cholangiocarcinoma (1 paper, 2022). A carcinoma that arises from the intrahepatic biliary tree (intrahepatic cholangiocarcinoma) or from the junction, or adjacent to the junction, of the right and left hepatic ducts (hilar cholangiocarcinoma). "It was found that inhibition of ECT2 promoted apoptosis of cholangiocarcinoma stem cells and inhibits tumor progression." (PMID 35722628, 2022).
clear cell renal cell carcinoma (1 paper, 2017). "In aggressive clear cell renal cell carcinoma, the ECT2 expression correlated with pituitary tumor-transforming 1 (PTTG1) expression and poor clinical outcomes, suggesting a possible downstream molecular mechanism whereby ECT2 promoted cancer malignancy." (PMID 28362321, 2017).
cyst (1 paper, 2015). A sac-like closed membranous structure that may be empty or contain fluid or amorphous material. "We found that CSPP-L accumulated in a punctuate staining pattern at the apical region of Caco-2 cells throughout different stages of cyst formation and that depletion of CSPP-L, but not Desmoplakin, is correlated with loss of ECT2 staining at apical cell-cell junctions." (PMID 26241740, 2015).
diffuse large B-cell lymphoma (1 paper, 2015). "In this study, we investigated the expression of FilGAP, with reference to the status of its associated molecules, including FLNa, integrin β2, epithelial cell transforming factor 2 (ECT2), and Rac1, in FL, diffuse large B-cell lymphoma (DLBCL), and peripheral T-cell lymphoma (PTCL)." (PMID 25641953, 2015).
endometrial cancer (1 paper, 2025). Primary or metastatic malignant neoplasm involving the endometrium (mucous membrane that lines the endometrial cavity). "Notably, the role and underlying mechanisms of ECT2 in endometrial cancer represent a critical area of uncertainty, necessitating focused and in-depth investigation." (PMID 40655948, 2025). "ECT2, firmly established as an oncogene, exhibits consistent overexpression across ovarian, cervical, and endometrial cancers, a phenomenon intricately intertwined with tumor initiation, malignant progression, and adverse patient prognosis." (PMID 40655948, 2025). "A study found through the analysis of differentially expressed gene (DEGs) data that ECT2 was highly expressed in atypical endometrial hyperplasia (AH) and endometrial cancer." (PMID 40655948, 2025). "ECT2 has high accuracy in differentiating benign and malignant endometrium and is expected to become a promising biomarker for the diagnosis of endometrial cancer and a prognostic indicator for endometrial cancer." (PMID 40655948, 2025). "And through the correlation analysis of the expressions of ECT2 and RhoA, ROCK1, and ROCK2 in endometrial cancer samples in TCGA database, it was found that the expression of ECT2 was significantly positively correlated with RHOA, ROCK1, and ROCK2." (PMID 40655948, 2025).
Fanconi anemia (1 paper, 2017). Fanconi anemia (FA) is a hereditary DNA repair disorder characterized by progressive pancytopenia with bone marrow failure, variable congenital malformations and predisposition to develop hematological or solid tumors.
lymph node metastasis (1 paper, 2021). "The histologic differentiation, TNM stages, and lymph node metastasis were related to ECT2 expression in GC patients." (PMID 34367280, 2021). "We also found that the high expression of ECT2 was related to lymph node metastasis and TNM stage in GC patients (p < 0.05)." (PMID 34367280, 2021).
malignant glioma (1 paper, 2021). A grade III or grade IV glioma arising from the central nervous system. "The ratios of PTBP2 exon 10 skipping/inclusion, INSR exon 11 skipping/inclusion (the ratio of INSR-A/INSR-B) and ECT2 exon 4 skipping/inclusion are indeed significantly increased in malignant glioma, especially in GBM patient samples when compared to normal brain." (PMID 34548489, 2021).
oral cancer (1 paper, 2010). "Little is known about the effect of a high level of ECT2 in regulating oral cancer cell behavior." (PMID 21124766, 2010).
oral squamous cell carcinoma (1 paper, 2010). "In this study, we investigated the involvement of ECT2 in oral squamous cell carcinoma (OSCC)." (PMID 21124766, 2010).
pancreatitis (1 paper, 2016). Inflammation of the pancreas. "These three genes, thus, may reflect different pathophysiological functions from the two genes, AHNAK2 and ECT2 that are increased to a similar degree in PDAC when compared to pancreatitis or healthy pancreas." (PMID 26993610, 2016). "AHNAK2 and ECT2 also showed elevated levels of expression in the matched PDAC tissue compared to normal or pancreatitis (fold change ~5-8), but the levels of these fold changes relative to normal and pancreatitis tissues were not significantly different." (PMID 26993610, 2016).
prostate (1 paper, 2024). "Studies investigating the role of ANLN and ECT2 in prostate carcinogenesis are diminutive." (PMID 38785827, 2024). "Thus, our novel findings lay the foundation to further elucidate the anti-proliferative effects of 1α,25(OH)2D3 in non-malignant prostate maintenance and prostate carcinogenesis by targeting potential survival PCa biomarkers, ANLN and ECT2." (PMID 38785827, 2024).
prostate adenocarcinoma (1 paper, 2024). "Prioritizing genes with vitamin D response elements and associating expression levels with overall survival (OS) in The Cancer Genome Atlas Prostate Adenocarcinoma (TCGA PRAD) cohort, we identified ANLN (Anillin) and ECT2 (Epithelial Cell Transforming 2) as potential prognostic PCa biomarkers." (PMID 38785827, 2024).
stomach adenocarcinoma (1 paper, 2021). "More importantly, upregulation of ECT2 has been found in stomach adenocarcinoma (STAD) and GC tissues." (PMID 34367280, 2021). "Compared with the control, the expression of ECT2 was increased in stomach adenocarcinoma (STAD) tissues (p < 0.05)." (PMID 34367280, 2021). "Upregulation of ECT2 was found in stomach adenocarcinoma (STAD) and GC tissues." (PMID 34367280, 2021).
Stroke (1 paper, 2012). Sudden impairment of blood flow to a part of the brain due to occlusion or rupture of an artery to the brain. "SMC4, NUF2 and ECT2 were augmented in the core and PI areas at 3 d after stroke." (PMID 23284893, 2012).
tumor (66 papers, 2010 to 2026). "For example, ECT2, a gene linked to tumor progression, has been shown to be expressed in a subset of mouse PRPCs and used as an example to show mouse RPC heterogeneity." (PMID 39117640, 2024). "Nevertheless, our study identifies ECT2 as an essential regulatory scaffolding protein in controlling the function of USP7, and indicates that ECT2/USP7 circuit is critically implicated in breast carcinogenesis." (PMID 32929379, 2020). "Regarding its role in tumor progression, ECT2 could associate with the PARD6A-PRKCI complex, which in turn stimulated RAC1 and finally induced cancer cell proliferation." (PMID 37106813, 2023). "ECT2 expression showed a strong correlation with tumor-associated macrophages." (PMID 33558466, 2021). "Guo and colleagues demonstrated that immunohistochemical staining for ECT2 on a human tissue microarray was positively associated with clinical pathological parameters such as Gleason score, pathological grade, clinical stage, tumor invasion, lymph node involvement, and distant PCa metastasis." (PMID 38785827, 2024). "Interestingly, the expression of ECT2, FGD6, MMP14, and SLC2A1 were statistically different in the patients with different tumor stage, which implied that ECT2, FGD6, MMP14, and SLC2A1 might be associated with the development of PC." (PMID 37604837, 2023). "Indeed, combined low miR-223 with high target mRNA ECT2 expression in osteosarcoma was significantly associated with tumour grade, chemo-resistance, development of metastases and tumour recurrence, as was in that same cohort, the combined low miR-183 with high target mRNA EZRIN expression." (PMID 26204834, 2015). "Knockdown of ECT2 inhibited 3D-transformed growth, invasion, and in vivo tumor formation while having little impact on PDAC cell cytokinesis." (PMID 42321532, 2026). "ECT2 has roles in controlling the cytoskeleton and is also studied for its involvement in tumor formation and progression." (PMID 39464883, 2024). "Tumor sphere formation assays demonstrated that the partial stemness of GINS2 KO cells was restored when ECT2 was overexpressed." (PMID 38467631, 2024). "GEPIA analysis identified three genes, ENG, GNG4, and ECT2, whose expression significantly differed between normal and tumor samples." (PMID 39552710, 2024). "Anillin and Ect2 redistributions scale with microenvironmental stiffness and confinement, and are observed in confined cells in vitro and in invading tumor cells in vivo." (PMID 38260442, 2024). "•The expression of ENG, GNG4 and ECT2 showed a significant difference between normal and tumor samples, have been identified by GEPIA analysis." (PMID 39552710, 2024). "Until the current stage, we have pointed out the upregulation of ECT2 in cancerous tissues versus normal samples and shown the correlation of that finding with the tumor stage, grade, patient prognosis, and immune reactivity." (PMID 37106813, 2023). "From this point, we aimed to correlate the expression of ECT2 in the tumor microenvironment with the infiltration of immune cells." (PMID 37106813, 2023). "Collectively, five tumors, namely ACC, KIRC, LIHC, LUAD, and PAAD, experienced a positive correlation between the ECT2 level and the tumor stage, based on the results from the two employed databases." (PMID 37106813, 2023). "The elevated levels of ECT2 in tumor tissues versus normal ones made us question the possible roles of ECT2 in patients’ survival; to answer that question we investigated two resources: GEPIA2 and a Kaplan–Meier (KM) plotter." (PMID 37106813, 2023). "The oncogenic behavior of these shared proteins was extended to ECT2; ECT2 regulates the Rho/ERK signaling axis to promote tumor recurrence and is associated with poor clinical outcomes." (PMID 37175004, 2023). "Following that, the study asked for the correlation between ECT2 upregulation and tumor stage, grade, and metastasis, along with its effect on patient survival." (PMID 37106813, 2023).
tumor (continued). "The output from the TISIDB web server demonstrated that there was a positive correlation between ECT2 expression and the tumor grade in KIRC, LGG, LIHC, UCEC (p < 0.001), PAAD, and HNSC (p < 0.01)." (PMID 37106813, 2023). "Then, we moved to correlate this overexpression with tumor grade and stage; the combined analysis showed that four human tumors, namely KIRC, LIHC, UCEC, and PAAD, experienced a positive correlation between ECT2 overexpression and both tumor grade and stage." (PMID 37106813, 2023). "In the current study, we employed a multi-omics analysis to assess the roles of ECT2 in tumor progression." (PMID 37106813, 2023). "Collectively, ECT2 experienced a hypomethylation and phosphorylation status in tumor conditions, a property that can be correlated with its overexpression and activity in cancerous tissues versus normal ones." (PMID 37106813, 2023). "ECT2 manifested remarkably high transcriptional level in poorly differentiated tumor (Pooled OR = 3.95, 95%CI 3.40–4.59) but low transcriptional level in ER + (Pooled OR = 0.45, 95%CI 0.39–0.53) and PR + (Pooled OR = 0.52, 95%CI 0.42–0.64) patients." (PMID 36572949, 2022). "In our study, the DEG analysis using GeneWalk showed 145 regulator genes in the HCV-related tumor group and 1 moonlighting gene (ECT2)." (PMID 36557005, 2022). "Compared with normal tumor cells, less apoptosis was observed in the tumor cells with ECT2 overexpression." (PMID 33558466, 2021). "The TIMER database was used to investigate the impact of ECT2 expression on tumor immune infiltration." (PMID 33558466, 2021). "The amount of lactate acid produced by tumor cells was significantly enhanced after ECT2 overexpression." (PMID 33558466, 2021). "As expected, increased TAM infiltration was observed in the normal HCC group compared to the ECT2 knockdown group, and ECT2 downregulation promoted tumor cell apoptosis and generated smaller-volume tumors." (PMID 33558466, 2021). "OTUB1-mediated deubiquitination of FOXM1 up-regulates ECT-2 to promote tumor progression in RCC, providing a new potential therapeutic target for RCC treatment." (PMID 32257108, 2020). "Our results showed that knockdown of FOXM1 decreased active GTP-loaded state of Rho (GTP-Rho and GTP-Rac1) in RCC, therefore inactivating ECT2-Rho signaling to suppress tumor growth." (PMID 32257108, 2020). "ECT2 is over-expressed in various tumors and functions as an oncoprotein to promote tumor progression." (PMID 32257108, 2020). "We then investigated on the function of ECT2 splicing isoforms in tumor growth of Doxo-resistant cells." (PMID 31943118, 2020). "SHCBP1, KIF4A, and ECT2 have been reported to mediate tumor initiation and progression of human HCC." (PMID 31392101, 2019). "Nuclear ECT2 can activate Rac1 in the cancer cells and recruit Rac effectors to the nucleus, which is required for tumor initiation and transformation." (PMID 29088286, 2017). "Fxr1 can also form a complex with PRKCI and ECT2, which controls cell proliferation/cell survival and links Fxr1 expression with human tumours; of note, elevated Fxr1 mRNA levels correlate with poor prognosis." (PMID 29142209, 2017). "NEK2, DLGAP5 and ECT2 expression levels were significantly elevated in tumor tissues compared with normal lung tissues." (PMID 28808310, 2017). "Among the clinical classifications, ECT2-positive OSCCs were correlated with tumor size (p = 0.043) and TNM staging of OSCC (p = 0.044)." (PMID 21124766, 2010). "Moreover, the disruption of both anillin and Ect2 functions profoundly affected the HT-1080 cancer cell invasion, resulting in a minimal number of invasive cells at the primary tumour front." (PMID 40571734, 2025). "This suggests that inducing tumor vascularization may act through a signaling pathway composed of ECT2, RhoA, RhoA-GTP, ERK, and VEGF/MMP." (PMID 40655948, 2025).
tumor (continued). "In the absence of nuclear Ect2 activity, LDAC TICs are unable to reconstitute tumor growth, emphasizing the essential role of Ect2 in promoting rRNA synthesis—a prerequisite for sustaining stem-like TICs in LADC—and underscoring the involvement of ribosome biogenesis in cancer stemness." (PMID 38633862, 2024). "Increased ANLN and ECT2 mRNA gene expression was significantly associated with PCa, and Gleason scores using both the TCGA cohort (p < 0.05) and an AA non-malignant/tumor-matched cohort." (PMID 38785827, 2024). "Increasing evidence suggests that the dysregulation of Ect2 correlates with many malignancies, and the suppression of Ect2 has been shown to impede tumor growth, indicating that ECT2 functions as an oncoprotein and plays a crucial role in cancer progression [48,51,]." (PMID 39552710, 2024). "In addition, ANLN and ECT2 expression was strongly correlated in both normal and tumor tissues, which is to be expected due to ECT2 forming a complex with ANLN to regulate cytokinesis." (PMID 38785827, 2024). "Finally, we applied the “compare tumor, normal, and metastasis” module of the TNMplot web server to study the correlation between ECT2 mRNA levels and cancer progression and metastasis." (PMID 37106813, 2023). "Moreover, the methylation and phosphorylation status of ECT2 in tumor versus normal tissue was assessed, in addition to the investigation of the ECT2 effect on the immune cell infiltration in the tumor microenvironment." (PMID 37106813, 2023). "We were also interested in studying the activation status, immune infiltration, genetic alteration, methylation condition, prognostic value, and molecular interactions of ECT2 in the tumor microenvironment to obtain an overview of the behavior of ECT2 in the tumor progression." (PMID 37106813, 2023). "Moreover, this overexpression predicted a progression in tumor stage and grade and a poor clinical outcome in a list of human tumors, where the genetic alterations in ECT2 also predicted poor patient survival." (PMID 37106813, 2023). "Besides normal cellular activity, ECT2 also participates in malignant transformation, tumor initiation, and metastasis." (PMID 36572949, 2022). "The proposed mechanism was verified by the results of in vivo experiments, which showed that ECT2 reduced the effect of decreased infiltration of M2 macrophages, promoted the apoptosis of tumor cells, and increased the activity of NK cells in the tumor microenvironment." (PMID 33558466, 2021). "Previous studies indicated that ECT2 may promote the polarization of M2 macrophages by enhancing aerobic glycolysis and inhibiting the functions of immune cells in tumor." (PMID 35284334, 2021). "In vivo subcutaneous xenotransplanted tumor model also revealed that knockdown of OTUB1 could suppress in vivo RCC growth via down-regulation of FOXM1-mediated ECT2 expression." (PMID 32257108, 2020). "Whether in GC tissue or serum, the expression of ECT2 was significantly higher than that of normal controls, and the expression of ECT2 was closely related to clinicopathological parameters including tumor grade, TNM stage, and lymph node metastasis." (PMID 33062405, 2020). "Knockdown of ECT2 inhibited tumor cell proliferation, migration and invasion." (PMID 32257108, 2020). "Notably, the tumor growth was greatly suppressed in athymic mice that received tumor transplants with ECT2-depleted cells." (PMID 32929379, 2020). "Regulation of ECT mRNA stability via FXR1 may also contribute to FXR1 oncogenic effects, while the tumour suppressor effects of miR-223 may be partly mediated by targeting the ECT2 3’UTR." (PMID 28806777, 2017). "NEK2, DLGAP5 and ECT2 were found to be highly expressed in tumor samples." (PMID 28808310, 2017). "Taken together, Ect2 may have oncogenic or tumor suppressive activities dependent on the cell contexts and the growth and stress conditions." (PMID 27074761, 2016).